PANX1 (pannexin 1)
Diseases named in the same sentence as PANX1 in open-access papers (continued):
Sharing a sentence is not in itself a finding about the gene and the disease.
tumor (continued). "During in vitro adenosine triphosphate (ATP) release and Yo-Pro-1 uptake assaysin a Panx1-expressing tumor cell line, both compounds were revealedto be promising bidirectional inhibitors of Panx1 channel function,able to induce a two-fold inhibition, as compared to the native 10Panx1 sequence." (PMID 37703077, 2023). "The single-cell transcriptome data revealed that TNBC tumor samples with high PANX1 expression had lower infiltration of B cells, CD4+ T cells, CD8+ T cells, myeloid cells, NK cells, and NK T cells and higher infiltration of cancer-associated fibroblasts (CAFs), plasma cells, and Tregs." (PMID 35884429, 2022). "Pannexin 1 (PANX1) is a critical ATP-releasing channel and widely participates in the regulation of the tumour immune microenvironment by infiltrating multiple immune cells, such as cancer-associated fibroblast cells, macrophage, lymphocytes, and neutrophil cells." (PMID 36601599, 2022). "However, the way in which PANX1 affects tumor-infiltrating immune cells (TIICs) and the immune TME by regulating exATP levels has not been reported." (PMID 35884429, 2022). "The findings might imply that PANX1 regulates ATP release and hence plays an essential role in tumor cells’ environment interaction." (PMID 34796785, 2021). "It seems that above all, the Panx1-HC/P2X7R signalosome may either induce the tumor growth and invasiveness by increasing extracellular ATP levels or suppress the IS by the conversion of ATP into ADO." (PMID 33806300, 2021). "As ectopic PANX1 effectively alleviates RMS tumor growth, deciphering its downstream signaling pathways would bring insight into the molecular mechanism by which PANX1 reduces RMS malignant properties while offering an opportunity to identify potential new therapeutic targets." (PMID 33564071, 2021). "Therefore, we performed a pan-cancer analysis of PANX1 using multiple databases to evaluate the features of gene expression, prognosis, and tumor immunity." (PMID 34796785, 2021). "PANX1-blocking therapeutics may be an effective strategy for tumor therapy, as previously discussed." (PMID 34796785, 2021). "Accumulating evidence suggests that PANX1 may enhance tumor proliferation, invasion, and metastasis by regulating extracellular ATP concentration in the TME." (PMID 34796785, 2021). "The findings showed that PANX1 may influence the development and prognosis of various tumors by regulating tumor immune cell infiltration in the TEM." (PMID 34796785, 2021). "PANX1 may promote tumor progression and immune suppression by co-expression of immunoinhibitors, such as CD274, PDCD1LG2, and TGFBR." (PMID 34796785, 2021). "Taken together these results suggest that FUS-induced ER calcium release mediated through mt PANX1 may play a key role in cancer cell invasion and tumor metastasis." (PMID 32656213, 2020). "The tumor volume in Panx1 knockout mice was significantly smaller than those in WT mice." (PMID 31737105, 2019). "To testify whether Panx1 overexpression contributes to tumor metastasis in vivo, we injected LM3-stable cells (overexpression and control) into the tail vein of nude mice." (PMID 31737105, 2019). "The tumor metastatic abilities were compared between Panx1 knockout mice and nude mice." (PMID 31737105, 2019). "Overall, these results revealed that PANX1 expression reduces RMS tumor growth in vivo." (PMID 30459312, 2018). "Notably, PANX1 expression also significantly reduced the growth of human eRMS and aRMS tumor xenografts in vivo." (PMID 30459312, 2018). "Importantly, in vivo data in a chick embryo xenograft model showed that reducing PANX1 expression reduced tumour growth and metastasis to the liver." (PMID 29865195, 2018). "This study suggests that Panx1 channels and ATP release may mediate paracrine interaction between dying tumour cells and leukocytes in anti-tumour responses." (PMID 29865195, 2018). "This suggests that the role of PANX1 in tumorigenesis may be complex and dependent on tumor type and stage of the disease." (PMID 27099931, 2016).
tumor (continued). "It remains interesting to speculate that PANX1’s role in regulating cell proliferation in normal development may translate into dysregulated growth in the context of the primary tumor." (PMID 27099931, 2016). "Similarly, in C6 glioma cells, Panx1 reintroduction significantly reduced cell proliferation, motility, and tumor growth in mouse models, indicating that its function may vary depending on cancer type and the surrounding microenvironment." (PMID 40978734, 2025). "In addition, Panx1 regulates tumor cell migration and invasion mainly by EMT signaling." (PMID 40909173, 2025). "We also assessed how PANX1 levels may correlate with tumour recurrence and size." (PMID 39560179, 2025). "PANX1 was prevalent in many tumour cell types in addition to the cSCC cancer cells such as in blood vessels and immune cells, meaning crosstalk between the different cell types within the tumour microenvironment may be possible." (PMID 39560179, 2025). "However, PANX1 was upregulated in PDAC tumor tissue and advanced stage samples." (PMID 39882247, 2024). "Interestingly, PANX1‐deficient BPC mice exhibited sex‐driven morphological differences in spleen size without an apparent influence on the tumor burden." (PMID 38327091, 2024). "We further hypothesize that ATP could be released via the transporter Pannexin 1, which was also upregulated in tumor cells (Log2FC 1.00, p.adj 2.76 × 10−4) and in turn activating purinergic receptors, such as P2RY13, while further inhibiting sodium transporters, such as SCNN1 components." (PMID 39038934, 2024). "Taken together, these results indicated that PANX1-mediated ATP release may enhance cancer immunogenicity and promote chemotherapy-induced antitumor immunity by recruiting DCs and T cells, and repolarization macrophage to eradicate tumor cells." (PMID 38195677, 2024). "Taken together, these results indicated that TNFα-mediated PANX1 cleavage to promote ATP release may enhance cancer immunogenicity and promote chemotherapy-induced antitumor immunity by recruiting DCs and T cells to eradicate tumor cells." (PMID 38195677, 2024). "In-depth investigations of PANX1 may help elucidate tumor-inflammation interactions." (PMID 35884429, 2022). "Our study first proposed that the high expression of PANX1 might be one of the reasons for high infiltration of immune cells but local immunosuppression in basal breast cancer, indicating PANX1 might play an important role in constructing pro-tumor TME." (PMID 35884429, 2022). "Therefore, Cxs and Panx1 could serve as potential molecular biomarkers of tumor prognosis and possibly as targets for future novel therapeutical approaches." (PMID 35682601, 2022). "However, the potential functions and mechanisms of PANX1 in tumor progression and tumor immunity remain unclear." (PMID 34796785, 2021). "In contrast, others have reported that PANX1 could be a tumor suppressor." (PMID 31817827, 2019). "In the xenografted tumors, the addition of PANX1 blockers not only affected tumor weight (and presumably growth), but also reduced the early stages of tumor migration and invasion, keeping the xenografted tumor borders intact and likely preventing the cancer cells from penetrating into the CAM." (PMID 30654593, 2019). "Notably, the C265S PANX1 mutant also had the ability to reduce RMS tumor growth in vivo." (PMID 30459312, 2018). "It is encouraging to think that Panx1 could be used as a biomarker in different cancers, but also as a conduit of ATP that assists the process of cancer cell death by existing chemotherapies, and facilitates immune recognition of the targeted tumour." (PMID 27229305, 2016). "Panx1 is one of the DAMPs molecules, activating the NOD1/NF-κB signaling pathway through ATP release, promoting tumor progression and immune regulation." (PMID 40909173, 2025). "Despite the larger N values of this study, PANX1 and PANX3 mRNA were detectable only in 31 normal tissue and 89 HNSCC tumour samples." (PMID 39560179, 2025).
tumor (continued). "To explore PANX1 and PANX3 transcript expression in patient‐derived cSCC tumours compared to normal skin controls, we first performed a bioinformatics search by investigating two cSCC RNA‐seq studies available on the GEO database." (PMID 39560179, 2025). "We used non‐adjacent normal skin samples as our control for this analysis, because it has been previously shown that PANX1 levels transiently upregulate at the site of cutaneous wounds in mice, and thus tumour‐adjacent skin may have increased PANX1 levels in response to the cSCC tumour." (PMID 39560179, 2025). "Conversely, Panx1 in U87MG cell influenced the release of glutamate and cytokines IL-6 and IL-8, acting anti-tumor effect." (PMID 40909173, 2025). "We examined the correlation between PANX1 expression and the infiltration of CD11+ DCs as well as CD8+ T cells within tumor tissues from CRC patients." (PMID 38195677, 2024). "Considering the interaction between tumor antigens and APCs, these potential antigens were further screened through the TIMER database where it was found that AGPS, NRAS, MTDH, PANX1, NOX4, and PPARD genes were positively correlated with different APCs." (PMID 38331967, 2024). "Using narrow-down analysis, six tumor antigens (AGPS, NRAS, MTDH, PANX1, NOX4, and PPARD) were found to be related to better prognoses as well as the infiltration of antigen-presenting cells in LUAD." (PMID 38331967, 2024). "To confirm the differences found in mRNA markers for T‐cell infiltration in tumors between Panx1 genotypes, we performed IF staining on PLP‐fixed tumor cryosections to verify the presence of CD4+, CD8+, and Foxp3+ lymphocytic cells." (PMID 38327091, 2024). "We found that knockdown of PANX1 significantly decreased the response to OXP, leading to a larger tumor size and tumor weight compared to those in the CT26shNC/OXP group." (PMID 38195677, 2024). "Similar to the mRNA levels, HSPA4, PANX1, and HSP90AA1 were significantly elevated in LUAD tumor tissues compared to normal tissues." (PMID 37259066, 2023). "Collectively, our results demonstrate the tumor-suppressive effects of quercetin in RMS and present a hitherto undescribed mechanism of PANX1 regulation via ETV4-mediated transcription of a translationally functional 5′ leader-containing PANX1 mRNA." (PMID 35194046, 2022). "Collectively, our results show for the first time the involvement of the PANX1 5′ UTR in regulating its mRNA translation and the tumor-suppressive effects of quercetin in RMS." (PMID 35194046, 2022). "EGLN1, MIF, PANX1, and RRM2 showed a consistently high expression in 15 tumor samples compared to paired normal tissues." (PMID 35311093, 2022). "The qPCR results revealed that the mRNA levels of RRM2, MIF, PANX1, and EGLN1 were significantly higher in tumor samples than in paired normal samples." (PMID 35311093, 2022). "We have previously shown that PANX1 overexpression in RMS cells reduced their proliferation, migration, and inhibited tumor growth via induction of apoptosis." (PMID 33564071, 2021). "However, the roles of PANX1 in tumor pathogenesis and immune infiltration remain unknown." (PMID 34796785, 2021). "We found that PANX1 expression is downregulated in patient-derived RMS cell lines and tumor specimens when compared to differentiated skeletal muscle cells and tissue." (PMID 33564071, 2021). "To further clarify the role of Panx1 in tumorigenesis, we established a tumorigenic model of subcutaneous nude mice with HCC cells and found that Panx1 promoted the tumor volume significantly." (PMID 31737105, 2019). "Altogether these studies indicate that Panx1/PANX1 expression and/or channel activity are altered in some forms of cancer, may be correlated with their aggressiveness, and that restoration of its levels and/or activity alleviate tumor malignant characteristics." (PMID 30459312, 2018).
tumor (continued). "Regardless, ectopic PANX1 had a potent inhibitory effect on several RMS malignant properties in vitro, which resulted in a significant reduction of tumor growth in vivo." (PMID 30459312, 2018). "Collectively, these findings suggest PANX1 and PANX3 dysregulation may have potential tumour‐promoting and tumour‐suppressive effects for keratinocyte transformation, respectively." (PMID 39560179, 2025). "Taken together, this indicates that in cSCC, PANX1 may exhibit pro‐tumour activities and PANX3 may exhibit anti‐tumour activities." (PMID 39560179, 2025). "Due to the short timeframe for tumor growth (~ 2 months) and given that the sexual dimorphism was found only in BPC‐Panx1−/− spleens, we speculate that characteristic developmental differences may account for this phenotype in Panx1−/− mice." (PMID 38327091, 2024). "We found that deleting the Panx1 gene in mice does not reduce BRAF(V600E)/Pten‐driven primary tumor formation or improve survival." (PMID 38327091, 2024). "Tumor size (median volume: 7.81 (min–max: 0.25–48 cm3)) did not correlate with Cx37 (p = 0.326), Cx40 (p = 0.893), Cx45 (p = 0.652), or Panx1 (p = 0.579)." (PMID 36833374, 2023). "And PANX1, PPIA and TLR2 were highly expressed in tumor group." (PMID 37259066, 2023). "EGLN1, MIF, PANX1, and RRM2 had higher expression in tumor than in normal samples." (PMID 35311093, 2022). "By using shRNA knockdown to reduce Panx1 levels in B16-BL6 cells, we observed a significant reduction in their malignant properties including decreased proliferation, migration and tumor size, as well as development of fewer metastases in the liver of a chick embryo model." (PMID 30654593, 2019). "In the present study, we determined that PANX1 transcript and protein levels are down-regulated in embryonal (eRMS) and alveolar RMS (aRMS) patient-derived cell lines and primary tumor specimens as compared to differentiated skeletal muscle myoblasts and tissue, respectively." (PMID 30459312, 2018). "Moreover, expression of channel-defective PANX1 mutants not only disrupted eRMS and aRMS 3D spheroids, but also inhibited in vivo RMS tumor growth." (PMID 30459312, 2018). "Despite a lack of differences seen in PANX1 mRNA levels (P = 0.9254) between tissue types, immunoblotting exhibited a significant increase in cSCC tumour PANX1 levels compared to patient‐matched normal skin (containing epidermis and dermis only) controls (P = 0.0011)." (PMID 39560179, 2025). "Notably, both studies contained small N values, and control tissues consisted of either paired human skin organoids or unpaired healthy skin, making it difficult to draw substantial conclusions about PANX1 and PANX3 expression in this cohort of patient‐derived cSCC tumours." (PMID 39560179, 2025). "This suggests that deletion of Panx1 alone may not influence Treg cell‐driven immunosuppression in this tumor model." (PMID 38327091, 2024). "As a limitation of this study, Panx1 gene deletion was not directed to any specific cell compartment; therefore, it is difficult to determine the specific impact of this deletion in the immune and tumor compartments distinctly." (PMID 38327091, 2024). "Mechanistically, evidence has suggested that ATP release from the P2X4R/P2X7R-gated Pannexin-1 channels can drive cell death via a mixed apoptotic and necrotic mode, which could be the reason why tumour necrosis was largely absent in the 5-BDBD-treated mice." (PMID 33233569, 2020). "Based on these findings, we hypothesized that the PANX1 tumor suppressive effects are independent of its channel function." (PMID 30459312, 2018). "Our findings also indicate that the tumor suppressive role of PANX1 does not require its canonical channel activity suggesting the existence of a novel, yet to be described, mechanism by which PANX1 functions." (PMID 30459312, 2018).
tumor (continued). "Collectively, these results confirmed that the deletion of Panx1 did not affect the infiltration of CD4+ and CD8+ T lymphocytes in the tumors, although the cytotoxic effect seemed to be insufficient to prevent the tumor progression in BPC‐Panx1−/− mice." (PMID 38327091, 2024).
cancer (59 papers, 2015 to 2025). A tumor composed of atypical neoplastic, often pleomorphic cells that invade other tissues. "Patients with low PANX1 expression in cancer cells or patients carrying P2RX7 polymorphism (E496A/rs3751143) had a better response to adjuvant chemotherapy associated with unfavorable survival outcomes." (PMID 38195677, 2024). "The release of cancer-associated ATP via caspase 3-gated PANX1 channels in response to chemotherapeutic drugs also enhances leukocyte recruitment and facilitates dendritic cell (DC) motility via the P2X7 receptor in response to danger signals." (PMID 38195677, 2024). "Altogether, these results imply that Panx1 contributes to genotoxic-induced IL-6 and is linked to poor clinical outcomes in cancer patients." (PMID 37696858, 2023). "To investigate the prognostic predictive ability of PANX1 in human cancers, we performed univariate survival analysis to determine the association between PANX1 expression and the overall survival (OS) of each cancer." (PMID 34796785, 2021). "In the majority of cancer types, PANX1 expression demonstrated a significant positive association with T cell regulatory using QUANTISEQ, but a negative correlation using CIBERSORT." (PMID 34796785, 2021). "PANX1 expression level was significantly related to infiltration of multiple immune cells in many cancers, including cancer associated fibroblast, macrophage, and neutrophil cells." (PMID 34796785, 2021). "PANX1 encodes a protein involved in intercellular communication, and mutations of this gene are associated with an increased expression of molecules involved in cancer growth." (PMID 36882567, 2023). "Given the emerging positive link between Panx1 expression and various cancers, it is possible that this metabolite is responsible for this trend." (PMID 40309905, 2025). "Panx1 is proposing as a valid immune-related therapeutic target for cancer due to regulating immune cells infiltration especially neutrophils." (PMID 40909173, 2025). "We determined that PANX1 channel activity promoted cancer cell properties such as growth and migration in SCC‐13 cells using established PANX1 channel inhibitors PBN and SPL." (PMID 39560179, 2025). "To assess the contribution of PANX1 channel function in SCC‐13 cancer cell properties, we utilized previously established PANX1 channel blockers PBN and SPL." (PMID 39560179, 2025). "In the context of cell migration and survival, Panx1 has also been shown to be crucial in the metastasis of various cancers." (PMID 40978734, 2025). "For example, the cell-surface channel protein pannexin-1 (PANX1) is involved in apoptosis and cancer progression." (PMID 41477487, 2025). "The finding of MTA as a novel Panx1-secreted metabolite opens a new area of inquiry into the role of this membrane channel in immune cell signaling, particularly as it relates to cancer." (PMID 40309905, 2025). "This highlights another possible mechanism for PANX1 to promote a survival advantage for cancer cells." (PMID 41250870, 2025). "Taken together, these results showed that TNFα administration enhances cancer immunogenicity via caspase-dependent PANX1 cleavage that mediates ATP release." (PMID 38195677, 2024). "Another interesting concept to consider is the consequence of inducing cancer cell death whilst modulating their removal by phagocytes, and/or metabolite release, and/or inflammasome activation through PANX1 blockade." (PMID 38336804, 2024). "PANX1 channels have attracted considerable attention due to their multiple roles in inflammation, cell death, and cancer." (PMID 38327091, 2024).